TRAV35 (T cell receptor alpha variable 35)
Description:
V region of the variable domain of T cell receptor (TR) alpha chain that participates in the antigen recognition. Alpha-beta T cell receptors are antigen specific receptors which are essential to the immune response and are present on the cell surface of T lymphocytes. Recognize peptide-major histocompatibility (MH) (pMH) complexes that are displayed by antigen presenting cells (APC), a prerequisite for efficient T cell adaptive immunity against pathogens. Binding of alpha-beta TR to pMH complex initiates TR-CD3 clustering on the cell surface and intracellular activation of LCK that phosphorylates the ITAM motifs of CD3G, CD3D, CD3E and CD247 enabling the recruitment of ZAP70. In turn ZAP70 phosphorylates LAT, which recruits numerous signaling molecules to form the LAT signalosome. The LAT signalosome propagates signal branching to three major signaling pathways, the calcium, the mitogen-activated protein kinase (MAPK) kinase and the nuclear factor NF-kappa-B (NF-kB) pathways, leading to the mobilization of transcription factors that are critical for gene expression and essential for T cell growth and differentiation. The T cell repertoire is generated in the thymus, by V-(D)-J rearrangement. This repertoire is then shaped by intrathymic selection events to generate a peripheral T cell pool of self-MH restricted, non-autoaggressive T cells. Post-thymic interaction of alpha-beta TR with the pMH complexes shapes TR structural and functional avidity.
Synonyms: TCRAV25S1; TCRAV35S1
Gene: T-cell receptor variable (V) pseudogene on chromosome 14 (22,221,896 to 22,222,475, forward strand). Ensembl gene ENSG00000211814.
Subcellular location: Cell membrane
Diseases named in the same sentence as TRAV35 in open-access papers:
TRAV35 is named in the same sentence as 1 disease in open-access papers, as found by Europe PMC text mining. Sharing a sentence is not in itself a finding about the gene and the disease.
TRAV35 shares sentences with these, for which no sentence is quoted: COVID-19 (1 paper).